EGFR (epidermal growth factor receptor)
Diseases named in the same sentence as EGFR in open-access papers (continued):
Sharing a sentence is not in itself a finding about the gene and the disease.
Hypomagnesemia (38 papers, 2010 to 2025). An abnormally decreased magnesium concentration in the blood. "Epidermal growth factor receptor (EGFR) inhibitors, such as cetuximab, panitumumab, and zalutumumab, are linked to renal magnesium wasting and hypomagnesemia." (PMID 40868117, 2025). "We examined the standards for magnesium supplementation, particularly as a countermeasure against hypomagnesemia caused by anti-EGFR antibody." (PMID 37878114, 2024). "Hypomagnesemia is believed to be caused by decreased activation of the renal EGFR, which results in lowered activation of the TRPM6 (transient receptor potential cation channel), leading to reduced reabsorption of Mg2+." (PMID 36077623, 2022). "Other classes of drugs including diuretics, gentamycin platinum-based cytostatic, calcineurin inhibitors, epidermal growth factor receptor (EGF-R) targeting drugs have been associated with hypomagnesemia." (PMID 35178215, 2022). "The severity of hypomagnesemia is associated with efficacy of EGFR inhibition and hypomagnesmia has been suggested to be a biological marker of therapeutic effectiveness in some cancers." (PMID 32706027, 2020). "One of the most significant electrolyte abnormalities associated with EGFR inhibitors in the treatment of cancer is renal magnesium wasting and hypomagnesemia." (PMID 30995736, 2019). "Hypomagnesemia during anti-EGFR therapy is mainly caused by a decrease in Mg reabsorption in the kidney." (PMID 27683640, 2016). "The timing of the onset of hypomagnesemia during treatment with anti-EGFR MoAbs can be inferred from the rate of magnesium loss and the duration of treatment." (PMID 20680104, 2010). "Therefore, patients treated with anti-EGFR antibodies are at risk of developing hypomagnesemia and concurrent hypocalcemia." (PMID 39639476, 2024). "Hypomagnesemia is associated with nausea and vomiting, fatigue, peripheral neuropathy, seizures, and QT prolongation, and severe cases lead to discontinuation of anti-EGFR therapy." (PMID 39696667, 2024). "A number of cancer-specific therapies can cause hypomagnesemia via renal magnesium wasting, including platinum-based chemotherapy, anti-epidermal growth factor receptor (EGFR) monoclonal antibodies, inhibitors of human epidermal growth factor receptor 2 (HER2), and calcineurin inhibitors." (PMID 34829467, 2021). "Agents, such as platinum-compounds and anti-EGFR Monoclonal Antibodies (MoAbs), causing hypomagnesemia may also induce hypocalcemia." (PMID 32509580, 2020). "For this CQ8, we searched for the literature, emphasizing suppression of hypomagnesemia exacerbation at hypomagnesemia onset during administration of anti-EGFR antibody drugs." (PMID 37878114, 2024). "Drug costs (unit cost) are relatively cheap, although it is unclear how entire costs during anti-EGFR antibody therapy can be reduced if aggravation of hypomagnesemia is suppressed." (PMID 37878114, 2024). "Regarding the anti-epidermal growth factor receptor (EGFR) monoclonal antibody panitumumab, electrolyte abnormalities, including hypomagnesemia, are reported among the characteristic side effects of anti-EGFR antibodies, while hypocalcemia is rarely reported." (PMID 39639476, 2024). "When anti-EGFR antibody is used in pharmacotherapy, hypomagnesemia is an adverse effect that is relatively common; it should be treated with caution since when it is severe, it can lead to arrhythmia." (PMID 37878114, 2024). "The intervention was well-tolerated and no adverse events were observed, such as those produced by other EGFR-targeting agents e.g., severe acneiform rash, hypokalemia, or hypomagnesemia." (PMID 36833093, 2023). "As far as anti-EGFR mAbs (panitumumab, cetuximab) are concerned, the most important renal AE of these therapies is dyselectrolytemia, in particular hypomagnesemia and hypokalemia." (PMID 36077623, 2022). "Electrolyte disorders including hypomagnesemia and hypokalemia are other AEs commonly observed in patients receiving EGFR inhibitor treatment." (PMID 35954563, 2022).
Hypomagnesemia (continued). "Cetuximab, a monoclonal antibody targeting EGFR, is known to promote the progressive development of hypomagnesemia due to renal magnesium wasting." (PMID 35779133, 2022). "Hypomagnesemia is often caused by the administration of anticancer drugs including CDDP and anti-EGFR antibody." (PMID 34066059, 2021). "Hypomagnesemia, by upregulating ROMK activity with ensuing potassium loss, is involved also in anti-EGFR MoAbs-induced hypokalemia." (PMID 32509580, 2020). "The adverse event of hypomagnesemia is comparatively frequent with anti-EGFR antibody treatment but is likely to be overlooked because it occurs in later treatment periods, and hypomagnesemia is asymptomatic until it becomes severe." (PMID 31637554, 2019). "Most clinical trials reported electrolyte disorders, particularly hypomagnesemia and hypocalcemia, in cancer patients treated with EGFR inhibitors." (PMID 30995736, 2019). "This mutation resulted in severe symptoms comparable to those observed with full EGFR blockade, including skin rash, inflammation of the lungs and bowel and hypomagnesemia." (PMID 27234911, 2017). "In a previous study, hypomagnesemia was reversible and complete recovery was seen once the anti-EGFR targeted agent was discontinued." (PMID 27683640, 2016). "The major mechanism of anti-EGFR antibody-related hypomagnesemia is suppression of EGFR-mediated urinary Mg(2+) reabsorption in both the renal tubule the intestinal tract." (PMID 27688901, 2016). "Hypomagnesemia is also an adverse effect of cancer treatment with biologics, in particular anti-EGFR mAb (cetuximab and panitumumab)." (PMID 25304221, 2014). "The impact of hypomagnesemia in patients undergoing anti-EGFR treatment for mCRC has been underestimated, most likely because magnesium levels are rarely measured during routine screening." (PMID 20680104, 2010). "Hypomagnesemia has emerged more recently as a side effect of EGFR inhibitors and should be considered in patients who develop fatigue and muscle weakness on therapy." (PMID 20680104, 2010). "In other clinical settings, such as treatment with platinum-based chemotherapeutic agents (e.g., cisplatin or carboplatin) or anti-EGFR therapies, as well as in cases of clinically significant hypomagnesemia, it is strongly advisable to closely monitor serum Mg2+ levels." (PMID 40732897, 2025). "Notably, the discontinuation of EGFR inhibitor therapy can reverse renal magnesium wasting and hypomagnesemia." (PMID 40868117, 2025). "Targeted therapies like epidermal growth factor receptor (EGFR) inhibitors, used in metastatic CRC, can cause electrolyte disturbances, particularly hypomagnesemia, which can prolong QT interval and increase the risk of fatal arrhythmias and sudden cardiac death." (PMID 41220414, 2025). "Hypomagnesemia induced by anti-EGFR antibodies is therefore considered due to TRPM6 dysfunction." (PMID 39696667, 2024). "An unexpected adverse effect of EGFR inhibition in cancer patients is hypomagnesemia." (PMID 32706027, 2020). "Hypomagnesemia is likely induced by several drugs including anti-EGFR antibodies." (PMID 31637554, 2019). "It is not possible to provide recommendations based on tests for administration and dosing of Mg during or after treatment with CDDP or anti-EGFR mAb, but all authors reviewed agree that hypomagnesemia must be corrected (level of evidence IV, grade of recommendation D)." (PMID 25304221, 2014). "Furthermore, several clinical studies reported hypomagnesemia due to renal Mg2+ wasting after treatment with EGFR-inhibiting antibodies." (PMID 23457647, 2013). "Consequently, hypomagnesemia may ensue due to diminished renal reabsorption of magnesium, a consequence of EGFR inhibition." (PMID 41049433, 2025). "Furthermore, regarding hypomagnesemia, a link has been suggested with the transient receptor potential melastatin (TRPM) 6 cation channel present in the distal tubules of the kidneys, and it has been reported that EGFR inhibitors cause downregulation of TRPM6." (PMID 40755575, 2025).
Hypomagnesemia (continued). "Generally, EGFR TKIs induced hypomagnesemia may be corrected by extra magnesium supplementation." (PMID 39026680, 2024). "However, there is no information in the literature regarding whether it was possible to continue the anti-EGFR antibody treatment or whether the treatment was interrupted or postponed after the onset of hypomagnesemia." (PMID 37878114, 2024). "Furthermore, hypomagnesemia and hypomagnesemia-induced QTc prolongation may lead to a loss of consciousness (LOC), but few papers have reported the association of anti-EGFR antibody treatment with the induction of loss of consciousness (LOC)." (PMID 31637554, 2019). "So far, no significant clinical trials have demonstrated a clear correlation between EGFR-TKI (gefitinib, erlotinib, or lapatinib) and hypomagnesemia." (PMID 39071492, 2024). "Inhibition of these processes with EGFR inhibitors decreases TRPM6 activity and reduces Mg2+ influx into cells, promoting Mg2+ excretion in the kidney with resultant Mg2+ wasting and hypomagnesemia." (PMID 30995736, 2019). "Furthermore, hypomagnesemia and hypomagnesemia-induced corrected QT (QTc) prolongation may lead to loss of consciousness (LOC), the onset of which is not generally considered associated with the treatment of anti-EGFR antibody because of its rare occurrence." (PMID 31637554, 2019). "Although hypomagnesemia is a documented side effect of anti‐EGFR antibody therapy, there have been no case reports of severe hypomagnesemia or its clinical course." (PMID 37042307, 2023). "The EGFR pathway is inhibited by anti-EGFR antibodies, which leads to an inhibition of magnesium reabsorption by transient receptor potential cation channel, subfamily M, member 6 (TRPM6) in the renal tubules, accompanying hypomagnesemia." (PMID 31637554, 2019). "Here, we inject mice with the anti‐EGFR monoclonal antibody ME‐1 for 2 weeks and observe a significant increase in serum Pi and mild hypomagnesemia, but no changes in Pi or Mg2+ excretion." (PMID 28292888, 2017). "For hypomagnesemia developing after administration of anti-EGFR antibody, additional magnesium supplementation has no apparent harm, and it may help avoid aggravation of hypomagnesemia." (PMID 37878114, 2024). "Erlotinib can affect magnesium hemostasis, but its effect on systemic magnesium concentrations does not appear to be as good as that observed in antibody-based EGFR inhibitors, and the erlotinib-induced hypomagnesemia may be corrected by magnesia supplementation." (PMID 39026680, 2024).
large cell carcinoma (38 papers, 2006 to 2026). A malignant epithelial neoplasm composed of large, atypical cells. "EGFR gene mutation rates according to histological subtype were 47.6% (305/641) for adenocarcinoma, 22.2% (2/9) for large cell carcinoma, and 13.3% (2/15) for other histological types." (PMID 28673332, 2017). "In these populations, the frequency of EGFR mutations in large cell carcinoma (LCC) patients was 11.5 and 3.6 %, respectively." (PMID 25086987, 2015). "EGFR mutations were predominantly observed in adenocarcinomas (77.8 %); however, two EGFR mutations were also detected in large-cell carcinoma metastases." (PMID 23892415, 2013). "We also identified that one of the 11 large-cell carcinomas, 2 of the 18 sarcomatoid carcinomas and 2 of the 11 mucoepidermoid carcinomas harbored TKIs sensitive EGFR mutations." (PMID 24351833, 2013). "EGFR mutations were found in 136 cases (42.2%) with adenocarcinoma, in one case with large cell carcinoma, and in one case with pleomorphic carcinoma." (PMID 16552419, 2006). "In a total of 469 tumours of the patients who underwent a surgical resection, EGFR mutations were found in 136 cases (42.2%) with adenocarcinoma, in one case with large cell carcinoma, and in one case with pleomorphic carcinoma." (PMID 16552419, 2006). "The histological features of the patient harboring EGFR exon 19 deletion was adenosquamous carcinoma with spindle cell and giant cell tumor and that of the patient harboring EGFR L858R mutation in exon 21 was large cell carcinoma with spindle cell and giant cell tumor." (PMID 26682906, 2015). "In a multivariate model, histology (large cell carcinoma, HR 2.2, 95% CI., 1.4–3.4, p<0.01), spinal bone metastasis (HR 1.7, 95% CI., 1.2–2.6, p<0.01), and mutational status (EGFR mutation, HR 0.3, 95% CI., 0.1–0.6 p<0.01) were significantly associated with survival." (PMID 23922984, 2013). "In addition, large cell carcinoma (LCC) rarely expressed EGFR mutations." (PMID 36233370, 2022). "We further used the SRB assay to examine the cytotoxic effect of WA in NSCLC cells, such as A549, CL141 and H441 (adenocarcinoma with wild-type EGFR), CL97 and H1975 (adenocarcinoma harboring EGFR T790M mutation), and CL152 (SCC) and H1299 (large cell carcinoma)." (PMID 31319622, 2019). "There were three (15.8%) EGFR mutations and four (21.1%) KRAS mutations in large cell carcinoma." (PMID 26486077, 2015). "Lysates from eight EGFR-mutant, four KRAS-mutant, and two EGFR/KRAS wild-type LUAD, as well as two large cell carcinoma and four SCLC cell lines were assessed." (PMID 34121659, 2021). "In this study, the effects of LCSE on EGFR signaling, cell proliferation, the cell cycle and apoptosis in A549 adenocarcinoma cells and NCI- H661 large-cell carcinoma cells were examined." (PMID 28056952, 2017). "The NSCLC cell lines HCC827 (EGFR mutant, adenocarcinoma), A549 (EGFR wt, adenocarcinoma) and NCI-H460 (EGFR wt, large cell carcinoma) were analyzed by SNP6.0 array." (PMID 26675484, 2015). "In this study, we could show that the combination of erlotinib with PS indeed exerts additive antineoplastic effects upon the EGFR-mutated adenocarcinoma cell line HCC827 and the EGFR wt adenocarcinoma cell line A549, whereas this effect was not seen in the large-cell carcinoma cell line NCI-H460." (PMID 26675484, 2015). "All the SCLC cell lines completely lacked EGFR protein expression and a large cell carcinoma with NE differentiation cell line, H1155, weakly expressed EGFR, whereas all other cell lines universally expressed high levels of EGFR." (PMID 34121659, 2021). "The PD-L1-high group contained two EGFR-mutant and five KRAS-mutant cell lines, the histological characteristics of which resulted six of them being classified as adenocarcinomas and one as a large cell carcinoma, while the PD-L1-low group contained only two KRAS-mutant adenocarcinoma cell lines." (PMID 27846317, 2016).
lung disease (38 papers, 2004 to 2025). "Numerous cells in the lung infected with SARS-CoV-2 cause EGFR overexpression, which contributes to worsening the pulmonary disease and triggering fibrosis." (PMID 36532549, 2022). "When performing EGFR mutation analysis in combination with sputum cytology, it is necessary to understand the cytomorphologic features and past history of lung disease in these patients." (PMID 33757469, 2021). "We reviewed 198 patients who were examined for EGFR mutation status and assessed the association of EGFR mutations with the underlying pulmonary diseases on chest high-resolution computed tomography (HRCT)." (PMID 22191026, 2011). "A case–control study revealed the main risk factors of CIP through prior lung disease, thoracic radiotherapy (RT), and combination treatment of ICIs or epidermal growth factor receptor (EGFR) tyrosine kinase inhibitors (TKIs), with odds ratios (OR): 2.86, 3.34, and 2.73, respectively." (PMID 36268845, 2022). "However, EGFR-regulated responses can become dysregulated and frequently exacerbated by advanced age and underlying lung disease, when the infectious burden becomes overwhelming." (PMID 35083168, 2021). "Other reports have also suggested that osimertinib may be associated with an increased incidence of pulmonary disorders relative to other EGFR-TKIs." (PMID 32517152, 2020). "From these data, we speculate that genetic variants that suppress neuregulin/EGFR/ErbB4 signaling may also contribute to severity of lung disease in a subset of infants with adverse respiratory outcomes." (PMID 30342483, 2018). "Therefore, we hypothesized that airway epithelial cell-specific deficiency of EGFR mitigates mucoinflammatory responses in Scnn1b-transgenic (Tg+) mice that phenocopy human CF-like lung disease." (PMID 40406132, 2025). "In this study, we investigated the role of airway epithelial cell-specific EGFR signaling in the pathogenesis of mucoinflammatory lung disease in Scnn1b-transgenic (Tg+) mice, a mouse model of human CF-like lung disease." (PMID 40406132, 2025). "However, the pathogenic role of EGFR signaling in mucoinflammatory lung diseases remains unknown." (PMID 40406132, 2025). "Accordingly, we investigated the role of airway epithelial cell-specific EGFR in the pathogenesis of mucoinflammatory lung disease in Scnn1b-transgenic (Scnn1b-Tg+) mice, a mouse model of human CF-like lung disease." (PMID 40406132, 2025). "The results from this study highlight the contribution of airway epithelial cell-specific EGFR in the pathogenesis of CF-like mucoinflammatory lung disease in Tg+ mice." (PMID 40406132, 2025). "Prospective studies of DNA methylation changes and lung disease are needed to assess the potential predictive ability of EGFR in lung disease." (PMID 35681244, 2022). "There is more knowledge about how VitD influences the EGFR locus gene, particularly in lung diseases, to control the proliferative activity of many different cancer cells." (PMID 36307516, 2022). "This is presumed from the knowledge of idiopathic interstitial pneumonia, as well as from the experience of the induction of lung disease by cytotoxic drugs, such as amiodarone, bleomycin, and epidermal growth factor receptor-tyrosine kinase inhibitor." (PMID 33964920, 2021). "AREG is involved in inflammation and repair responses through autocrine and paracrine activation of EGFR, and generally induced in lung disease." (PMID 29540993, 2018). "C/EBP transcription factors also modulate inflammatory gene expression in lung diseases, and here we found that casticin represses C/EBPβ and EGFR inflammatory gene expression in A549 cells." (PMID 29254155, 2017). "A study in a population with a high co-incidence of pulmonary disease proposed that the mechanism for developing epidermal growth factor receptor (EGFR) tyrosine kinase inhibitor (TKI)-induced ILD was most likely related to a decrease in alveolar regeneration." (PMID 24348843, 2014).